CDC20 (cell division cycle 20)
Diseases named in the same sentence as CDC20 in open-access papers (continued):
Sharing a sentence is not in itself a finding about the gene and the disease.
cancer (continued). "CDC20 (cell division cycle 20 homologue) is a regulatory molecule performing critical activities in several parts of the cell cycle, human tumorigenesis and cancer progression." (PMID 34895070, 2021). "To be more specific, we hypothesized that the increased expression of CDC20 in the high pathological stage could be diluted by the normal expression of CDC20 in the early stage of cancers." (PMID 34527589, 2021). "In the end, the molecular function of Cdc20 in pan-cancer analysis indicated that BUB1, CCNA2, CCNB1, CDK1, MAD2L1, and PLK1 might play a critical role in its oncogenic function." (PMID 34527589, 2021). "Therefore, CDC20 expression can be used as a biomarker for tumor prognosis and a therapeutic target for human cancers." (PMID 34753395, 2021). "In addition, we further compared the translational expression of Cdc20 across 15 familiar cell lines in cancer research to select the optimal model for the functional analysis of Cdc20." (PMID 34527589, 2021). "CDC20 inhibitors are in development for the treatment of human cancers." (PMID 33851100, 2021). "Firstly, we generate a ranking list of cancer types in order of CDC20 gene expression." (PMID 34527589, 2021). "Notably, our results showed that the high expression of CDC20 was negatively correlated with OS in multiple cancer types, including ACC, KIRC, KIRP, LGG, LIHC, LUAD, MESO, and SKCM." (PMID 34527589, 2021). "Therefore, our studies delineated the oncogenic role of CDC20 and its prognostic significance at the pan-cancer level and proved its functional activity in Cdc20 high expression cancer types." (PMID 34527589, 2021). "This sequestration keeps Cdc20 away from the anaphase-promoting complex/cyclosome degradation system, thereby interfering with mitosis exit and promoting chromosome missegregation in cancer cells." (PMID 34922589, 2021). "Increasing evidence showed that Cdc20 exhibits an oncogenic function and targeting Cdc20 could be a novel strategy for combating human cancers." (PMID 34527589, 2021). "Accumulating evidence have shown that CDC20 is frequently overexpressed in a wide range of cancers, indicating that it might function as an oncoprotein." (PMID 33130827, 2021). "Here, a pan-cancer analysis was performed to analyze the role of Cdc20 in various human cancers." (PMID 34527589, 2021). "Cell division cycle 20 (CDC20) is a regulatory molecule that plays critical roles at multiple points of the cell cycle and may serve an oncogenic role in human cancer." (PMID 33408743, 2020). "It was reported that CDC20 is significantly overexpressed in different cancer types." (PMID 32932732, 2020). "Many studies indicate that Cdh1 functions as a tumor suppressor, whereas CDC20 may function as an oncoprotein to promote the development and progression of cancers." (PMID 33643919, 2020). "As a result, the development of specific CDC20 inhibitors may provide a new approach to treat human cancers by virtue of elevated CDC20 expression." (PMID 32219041, 2020). "Abnormal expression of CDC20 appears in most of the human cancers." (PMID 33102593, 2020). "TCGA transcriptome data indicate that CDC20 is highly expressed in human cancers." (PMID 32932732, 2020). "CDC20 ablation induces complete metaphase arrest and cell death in cancer cells." (PMID 32637030, 2020). "This suggests that CDC20-dependent activation of the APC may be a critical component of cancer development and behavior." (PMID 32805721, 2020). "The functional role of CDC20 has been reported in the cell cycle, proliferation, and apoptosis, and it may present a potential novel cancer therapeutic strategy as a candidate target." (PMID 32040444, 2020). "Therefore, CDC20 is with great potential to be further explored as a candidate biomarker and potential cancer therapeutic target in BC." (PMID 32677673, 2020). "Next, we focused on whether mRNA expression of CDC20 was related to cancer stage in individual patients." (PMID 32285914, 2020).
cancer (continued). "Given its potential role in resistance to radiation, the CDC20/Mcl-1/p-Chk1 pathway might be a promising target to overcome radioresistance and increase the efficacy of cancer therapy." (PMID 32932732, 2020). "It has been reported that CDC20 may act as an oncoprotein to promote the progression and development of human cancer and that it is a promising therapeutic target." (PMID 32047816, 2020). "In addition to regulating cell cycle, recent evidence has demonstrated that CDC20 also plays an important role in carcinogenesis and cancer progression, having the potential to become a promising therapeutic target." (PMID 32285914, 2020). "Hence, the development of more efficient Cdc20-APC/C inhibitors or the development of new strategies to target Cdc20 are urgently needed to enhance cancer therapeutics via mitotic catastrophe." (PMID 31669221, 2019). "Compared to adjacent non-cancerous tissue samples, CDC20 was overexpressed in primary cancer tissues, and it was significantly associated with clinical stages, lymph node status, and pathologic differentiation." (PMID 31106147, 2019). "Thus, deprivation of the mitotic role for Cdc20-APC/C by either inhibition of Cdc20-APC/C activity or elimination of Cdc20 protein via induced protein degradation emerges as an effective therapeutic strategy to control cancer." (PMID 31669221, 2019). "The top 1 network in the spleens of A.SW mice was categorized as “Cell Cycle,” “Reproductive System Development and Function,” and “Cancer,” including down-regulated genes: cyclin family (Ccne1, Ccnb1, and Ccnb2) and cell division cycle family (Cdc20, Cdc25b, and Cdc25c)." (PMID 30941144, 2019). "Furthermore, Cdc20 levels are highly regulated, unlike most other checkpoint components, and Cdc20 is known to be overexpressed in several cancers, which calls for an investigation on the effect of high levels of Cdc20 on mitotic checkpoint activity." (PMID 30199529, 2018). "The recent studies have shown that CDH1 is functioning as a tumor suppressor whereas CDC20 may function as an oncogene to promote the development and progression of human cancers." (PMID 30563222, 2018). "However, an alternative interpretation is possible to explain why CDC20 accumulates in cancer cells." (PMID 29954095, 2018). "Thus, our results demonstrate that Cdc20 augments cancer cell invasion through proteasomal degradation of SMAR1, at least in part." (PMID 28617439, 2017). "We found that curcumin inhibited the Cdc20 expression, leading to anti-cancer activity in PC cells." (PMID 28165402, 2017). "It is important to discover the inhibitors of Cdc20 for the treatment of human cancers." (PMID 28165402, 2017). "Recently, CDC20 has been suggested to be a potential novel cancer therapeutic target." (PMID 28830341, 2017). "Cdc20 is highly expressed in many types of cancer, including GBM." (PMID 26993778, 2016). "withaferin A exerted its anti-cancer activity through enhanced degradation of Cdc20 and Mad2." (PMID 27626499, 2016). "CDC20 protein level may directly influence the fate of cells during prolonged mitotic arrest and its turnover rate may critically affect the response of a cancer patient to anti-mitotic therapies." (PMID 26817825, 2016). "Since Cdc20 is identified as an oncoprotein in tumorigenesis, inactivation of Cdc20 could be useful for the treatment of human cancers." (PMID 27626499, 2016). "Several natural agents were identified to inhibit the Cdc20 expression in human cancer cells." (PMID 27626499, 2016). "Several studies suggest that the APC/C and its co-activator Cdc20 could be potential new therapeutic targets in cancer." (PMID 26716651, 2016). "Further studies revealed that targeting Cdc20 could be a novel therapeutic approach in human cancers." (PMID 27626499, 2016).
cancer (continued). "We also considered the analysis of recurrence of cancer, and we found that the level of gene expression in the normal tissue was associated with recurrence for many genes: FOXC2, CDC20, OCLN and SERPINB2 (p = 0.0067, p = 0.0067, p = 0.048 and p = 0.0352 respectively)." (PMID 25575813, 2015). "CDC20 is a central regulator of the cell cycle in numerous cancers." (PMID 25938542, 2015). "Their studies suggest that HEC1, MAD2, and CDC20 may be involved in NEK2A induced CIN in cancer cells." (PMID 25705694, 2015). "Moreover, elimination or blocking of CDC20 in several cancer models results in mitotic arrest and apoptosis." (PMID 26561808, 2015). "Elevated levels of CDC20 have been found in a wide variety of cancers." (PMID 26561808, 2015). "CDC20 protein level may directly affect cell fate during prolonged mitotic arrest and its turnover rate may be a key factor in cancer patient response to antimitotic therapies." (PMID 25210704, 2014). "Recent studies have shown that CDC20 may function as an oncoprotein, promoting the development and progression of human cancers." (PMID 24748173, 2014). "Furthermore, expressions of specific genes including CDC20 consistently correlate with total functional aneuploidy and are predictive of poor prognosis in several cancer types using a computational method." (PMID 23738901, 2013). "Further studies are required to investigate how CDC20 is regulated in cancer cells." (PMID 23758705, 2013). "The proposed antagonistic relationship between this enzyme and USP44 raise the possibility that alterations in the ubiquitination status of Cdc20-APC/C or its substrates may be a recurring theme in a number of cancers." (PMID 21853124, 2011). "Thus, the discovery of new layers of CDC20 regulation might help to develop new strategies to target this key cell cycle regulator in cancer therapy." (PMID 38523261, 2024). "Next, we explored whether CDC20 has a potential effect on the chemosensitivity of cancer cells." (PMID 39125953, 2024). "Therefore, impaired CDC20 function may terminate mitotic arrest and lead to the initiation and progression of cancer." (PMID 39061186, 2024). "Hence, this oncogene is considered a potential therapeutic target for various aggressive cancer types, and the development of CDC20 inhibitors could be a novel avenue that proceeds from preclinical to clinical studies to treat tumors." (PMID 39061186, 2024). "Indeed, the substantial role of elevated CDC20 mRNA expression in BC progression and poor clinicopathological features was previously cited, as it was considerably more prevalent in patients with large tumor sizes and high-grade primary malignant tumors." (PMID 39061186, 2024). "In addition, even when using an appropriate concentration (20 μM) of cisplatin or etoposide to treat cancer cells, higher levels of γH2AX protein could still be detected in CDC20 knockdown cells." (PMID 39125953, 2024). "Cdc20 may be a promising target for the treatment of cancer." (PMID 37259447, 2023). "Furthermore, multiple studies have revealed that CDC20 promotes proliferation, invasion, and metastasis of cancer cells through the CDC20-meidated angiogenesis pathway, indicating that CDC20 can promote angiogenesis in cancer tissues." (PMID 37682144, 2023). "Thus, uncovering the mystery by which aberrant accumulation of CDC20 drives drug resistance could lead to a new therapeutic strategy for cancer control." (PMID 35954396, 2022). "Amplified CCT expression in cancer cells could, therefore, directly promote cell cycling by folding essential substrates like tubulin or cdc20 and indirectly through interactions with transcription factors like MYC, and promoting the expression of cell cycling factors like cyclin D." (PMID 35602608, 2022). "Recent studies indicated that CDC20 may serve an oncogenic role in various types of human cancer." (PMID 35360870, 2022).
cancer (continued). "Suppressing CDC20 (depletion of endogenous or pharmacological inhibitors) in diverse cancer cell lines led to a mitotic arrest and apoptosis, suggesting targeting CDC20 might be a novel anti-cancer therapy, especially in cancer with high expression." (PMID 35875102, 2022). "Moreover, CDC20 was also reported to be an oncogene in several kinds of cancer including HCC." (PMID 35622386, 2022). "Thus, genetic and/or pharmacologic interventions aimed at inhibiting Cdc20-APC/C-securin signaling may be a valid strategy to either enhance cancer cell death induced by chemotherapeutic drugs or limit undesired side effects caused by chemotherapy in NSCLC." (PMID 35988650, 2022). "Moreover, Cdc20-APC/C plays a key role in cancer progression and drug resistance." (PMID 35680848, 2022). "Moreover, the phosphorylated Cdc20 could be more functional active in performing its oncogenic role in cancer." (PMID 34527589, 2021). "However, the exact role and landscape of CDC20 gene expression and its biological impacts across different types of cancers remains largely unknown." (PMID 34527589, 2021). "Back in 2015, there were reports that CDC20 could be used as a novel cancer treatment modality." (PMID 33912448, 2021). "Thus, the blockade of Cdc20 by small molecular inhibitors could be a plausible therapy in the indicated cancer types." (PMID 34527589, 2021). "CDC20 is the mitotic checkpoint and a cellular safeguard that prevents chromosome mis-segregation in eukaryotic cells, and suboptimal functioning of this checkpoint may promote chromosome mis-segregation in cancer cells." (PMID 32322666, 2020). "Therefore, various studies considered CDC20 as a therapeutic target for cancer treatment." (PMID 31681566, 2019). "Therefore, Cdc20 is perceived as a promising therapeutic target for cancer therapy." (PMID 31669221, 2019). "Hence, CDC20 may represent a promising therapeutic target in cancer patients including those with PDAC." (PMID 30765611, 2019). "Thus, Cdc20 is thought to be a potential biomarker and an ideal target for cancer therapy." (PMID 31669221, 2019). "CDC20 may function as an oncoprotein to promote the development and progression of human cancers." (PMID 30363964, 2018). "Therefore, elevated CDC20 expression could reflect APCCDH1 impairment in cancer cells, inferring that APC activation will be beneficial to cell health." (PMID 29954095, 2018). "Furthermore, we find that the presence or absence of one specific assembly reaction determines whether the checkpoint remains functional at elevated levels of Cdc20, which can occur in cancer cells." (PMID 30199529, 2018). "Importantly, we also show that inhibition of Cdc20 promotes mitotic cell death more effectively than loss of APC/C activity through differential effects on Mcl‐1 degradation, providing an improved strategy to kill cancer cells." (PMID 29987118, 2018). "Recent studies have suggested that CDC20 might be a potential target for cancer therapy." (PMID 23758705, 2013). "CDC20 could be a potential target for development of anti-cancer agents." (PMID 22475564, 2012). "To further explore the respective roles of CDC20 and the APC/C in response to SAC inhibition, we analyzed genomic and transcriptomic datasets from over 1700 human cancer cell lines from the cancer Dependency Map." (PMID 39838194, 2025). "Inhibiting APC/C activity with agents like proTAME, which blocks its activation via CDC20 and CDH1, opens new avenues for disrupting cancer cell proliferation and invasion." (PMID 40136519, 2025). "Our study provides valuable insights into the role of CDC20 in DIC and contributes new information on potential molecular mechanisms and pathways that underpin DIC, which may lead to risk mitigation and the development and refinement of effective cancer therapies." (PMID 40045239, 2025). "Next, Spearman correlation analysis across 189 pan-cancer single-cell datasets revealed a positive correlation between WDR77 and CDC20 (r = 0.42, P < 0.001)." (PMID 41425556, 2025).
cancer (continued). "The inclusion of genes like AK5, CDC20, and TFF3, which have established roles in cancer cell proliferation and metastasis, underscores their importance in a predictive model." (PMID 40161494, 2025). "Additional evidence for the antiproliferative potential of phenylpropanoids comes from studies on cinnamaldehyde and its analogs, which induced G2 arrest in human cancer cells by downregulating key G2/M regulators (CDK1, CDC25C, MAD2, CDC20)." (PMID 41009502, 2025). "We therefore compared CDC20 and APC/C mRNA expression levels between the top and bottom aneuploid quartiles of human cancer cell lines in the DepMap." (PMID 39838194, 2025). "Investigating the expression of CDC20 in several clinicopathological features using the TCGA database and UALCAN analysis indicated the upregulated level of CDC20 in BC malignant tumors compared to normal tissues, as validated using IHC images." (PMID 39061186, 2024). "Similar to CDC20, overexpression of UBE2C has been observed in different cancers, fueling cancer cell proliferation." (PMID 38462627, 2024). "The two marker FDGs in HDFM, CDC20 and UBE2C had been previously reported to have a strong correlation in 27 cancers." (PMID 38462627, 2024). "First, inhibition of the CDC20 oncoprotein by silencing suggests that, since it is an APC activator, the APC itself must be a critical driver of cancer development." (PMID 38730707, 2024). "Specifically, we seek to understand the connection between CDC20 and CCNB1 and higher tumor grade and cancer stage." (PMID 39795587, 2024). "Cancer-related genes such as CXCR4, MMP7, CDC20 and CDK6, and unfolded protein response (UPR)-related genes such as ATF3, ATF4, XBP1 and CHOP, showed significant differences in expression in the indicated cells." (PMID 38263248, 2024). "The aim of this study is to evaluate the relative changes in the expression levels of CDC20 and CCNB1 genes among tumor grades and cancer stages in patients with BC." (PMID 39795587, 2024). "Taken together, our findings demonstrated a molecular rationale for combining a Cdc20 inhibitor with a UPR activator and offered a novel strategy for cancer therapy." (PMID 39401430, 2024). "Therefore, CDC20 inhibitors may be an ideal therapeutic strategy to block cancer cell growth." (PMID 37682144, 2023). "By cDNA microarray analysis, M3-HBx and CtHBx significantly up-regulated the expression of plasminogen activator inhibitor-1 (PAI1) and cell division cycle 20 (CDC20) in the liver and induced pro-cancer inflammation to promote carcinogenesis." (PMID 36672482, 2023). "To date, growing evidence indicates that overexpression of Aurora A/B, cyclin D/E, Cdc20, Skp2, and PLK1 has been frequently detected in all kinds of cancers, and these oncoproteins serve as effective therapeutic targets in the clinic." (PMID 37274251, 2023). "SCL/TAL1 interrupting locus (STIL) promotes proliferation, invasion, and cancer progression by regulating the expression of CDK1, CCNB2, CDC20, CCNA2, BUB1, and AURKB." (PMID 36661515, 2023). "The CDK1, CDK5, CDC20, CCNA2, CCNB1 and CCNB2 expression levels (tumor sample: n = 369 vs. normal sample: n = 160) were upregulated in HCC group compared with the non-carcinoma group (Analysis by GEPIA dataset)." (PMID 36605491, 2023). "Beyond its mitotic function, the role of CDC20-APC/C has been documented to regulate a series of cellular processes, including apoptosis, brain development, cancer stem cell proliferation, and genome stability." (PMID 35954396, 2022). "From the perspective of bone and cartilage changes, CDC20 and TOP2A, which are related to cancer cell proliferation and progression, were recently suggested to play a role in rat bone marrow stem cell osteogenesis and chondrogenesis." (PMID 36700234, 2022). "In the PPI networks, we identified four key molecules (PAI1, CDC20, P21, and SKP2) whose expressions were dysregulated the HBx mutants in the two human cancer cell lines." (PMID 35223517, 2022).